ALB (albumin)
Diseases named in the same sentence as ALB in open-access papers (continued):
Sharing a sentence is not in itself a finding about the gene and the disease.
lymphopenia (continued). "The top-ranked features in order of importance were NLR, age, albumin, number of involved organs, number of prior chemotherapy regimens, ECOG performance status, lymphopenia, and use of multi-session PRT." (PMID 41341340, 2025). "After subsequent stepwise selection, the final model consisted of four independent predictors of delayed lymphopenia, lower baseline and during-CRT ALC, lower during-CRT albumin, and higher lung V5." (PMID 36059659, 2022). "Her laboratory abnormalities showed lymphopenia, high levels of ferritin, D-dimer, CRP, AST, ALT, and BUN, and a low serum albumin level." (PMID 36553314, 2022). "Older age, co-morbidities, smoking history, concomitant administration of NSAIDs, lymphopenia, high LDH, low albumin, and advanced malignancies." (PMID 35892857, 2022). "Laboratory findings vary from leukocytosis, leukopenia, lymphopenia, elevated AST, reduced albumin, elevated LDH, elevated CRP, and elevated ESR." (PMID 34786427, 2021). "We also observed raised MCHC, a reduction in eosinophils, low albumin levels, high CRP, and lymphopenia." (PMID 34031483, 2021). "Laboratory findings such as lymphopenia (N=19), elevated C-reactive protein (N=29); alanine aminotransferase (ALT) and aspartate aminotransferase (AST) (N=3) and decreased Albumin (N=1) were reported in most studies." (PMID 32440660, 2020). "Furthermore, we found that patients in the persistent lymphopenia endotype also had higher CRP levels and lower pre-albumin levels after admission to ICU than other endotype patients." (PMID 35991659, 2022). "Neutrophilia (>80% neutrophil), lymphopenia (<20% lymphocyte), hypoproteinemia (<6.4 gm/dl protein), and hypoalbunemia (<3.4 gm/dl albumin) were significantly more common in the non-survivors." (PMID 34646702, 2021). "Most patients demonstrated lymphopenia with marked CRP and D-dimer increases and albumin decreases." (PMID 33102532, 2020). "Likewise, in line with the literature information, we identified a correlation between acute phase reactants and inflammatory biomarkers including leukocytosis, lymphopenia, CRP, cardiac troponin, D-dimer, fibrinogen, lactate dehydrogenase, ferritin, and serum albumin and mortality." (PMID 33315349, 2021). "The median albumin level was 36.13 g/L (IQR [28.12–44.52]) in patients with lymphopenia, which was significantly less than patients with no lymphopenia (P = 0.001)." (PMID 33206680, 2020).
Pleural effusion (137 papers, 2010 to 2026). The presence of an excessive amount of fluid in the pleural cavity. "A binary logistic model was used to evaluate risk factors for post operative pleural effusion among patients with postoperative fibrinogen, albumin, protein, INR, APTT, platelets, and Hemoglobin level." (PMID 42257075, 2026). "While elevated CRP levels, low lymphocyte count, and reduced albumin levels were associated with pleural effusion, only lymphocyte count (cut-off < 0.605 109/L) remained an independent predictor in the multivariate analysis." (PMID 40428888, 2025). "A previous study revealed that key risk factors include older age, pleural effusion, pulmonary hypertension, low serum albumin and decreased eGFR." (PMID 40589976, 2025). "We also identified rarely expressed modifiable risk factors, such as serum albumin level, that play a role in left-sided pleural effusion development." (PMID 39336439, 2024). "This study has identified several clinical factors, such as chest tightness, long duration of fever, low serum albumin, and low blood sodium, as risk factors for the development of pleural effusion in elderly patients with CAP." (PMID 37730573, 2023). "Their research identified respiratory rate, dyspnea, lung moist rales, LDH, BUN, CRP/ALB ratio, and pleural effusion as potential predictors for ICU admission risk." (PMID 37685276, 2023). "Low circulating serum albumin is associated with pleural effusion, oedema and vascular constriction as a result of serum albumin being sequestered within the interstitial tissues." (PMID 35456942, 2022). "The fall in albumin likely has several causes, including the inhibition albumin synthesis, sequestration of albumin in ascites or pleural effusions, and bowel obstruction." (PMID 32723677, 2020). "In conclusion, our data showed that POD2ALB is inversely associated with pleural effusion, and that intraoperative albumin infusion is associated with a lower incidence of pleural effusion when compared to synthetic colloid infusion in liver donors." (PMID 30808903, 2019). "We first analysed the association between postoperative albumin level and the development of pleural effusion in the donors who underwent hepatectomy from 2004 to 2012 (n = 2046)." (PMID 30808903, 2019). "The use of albumin was associated with significantly reduced incidence of postoperative pleural effusion before (OR 0.63, 95% CI 0.46–0.84; P = 0.002) and after PS matching (OR 0.61, 95% CI 0.41–0.92; P = 0.018) when compared to synthetic colloid use." (PMID 30808903, 2019). "In multivariable analysis, the lowest albumin level within POD2 (POD2ALB) was inversely associated with pleural effusion (OR 0.28, 95% CI 0.20–0.38; P < 0.001)." (PMID 30808903, 2019). "Previous co-morbid, vomiting, diarrhoea, pleural effusion, low systolic blood pressure, high haematocrit, low albumin and high urea were found as significant risk factors for severe dengue using simple logistic regression." (PMID 27551776, 2016). "Previous co-morbid, vomiting, diarrhea, pleural effusion, low systolic blood pressure, high hematocrit, low albumin and high urea were found as significant risk factors for severe dengue using simple logistic regression." (PMID 27551776, 2016). "Pre-operative variables including weight loss, low serum albumin and pre-albumin, Geansler’s index, postoperative chylothorax, pleural effusion, and hospital stay, are predictive of mortality in patients who undergo esophagectomy for esophageal cancer." (PMID 20871187, 2010). "Additionally, increased ADM concentrations correlate with low albumin levels and greater pleural effusion, reflecting its association with organ dysfunction." (PMID 39458091, 2024). "A decrease in albumin can cause a decrease in plasma colloid osmotic pressure, leading to the retention of a large amount of fluid in the tissue gap, which is prone to pleural effusion and pulmonary edema, providing favorable conditions for the proliferation of pathogens." (PMID 39776439, 2024).
Pleural effusion (continued). "Pathogenesis of pleural effusion and pulmonary edema has been explained to be multifactorial, which includes increased hydrostatic pressure due to volume overload and decreased plasma oncotic pressure owing to albumin loss through urine." (PMID 34249571, 2021). "Therefore, we sought to investigate the association of early postoperative albumin level with the development of pleural effusion after donor hepatectomy for LDLT." (PMID 30808903, 2019). "A low level of serum albumin usually causes low oncotic pressure and might thereby increase the transudative pleural effusion." (PMID 31194145, 2019). "Interestingly, indicators of plasma leakage (pleural effusion index and nadir albumin levels) showed statistically significant associations only with viral RNA levels in plasma and CD14+ cells." (PMID 23284680, 2012). "We speculated that the lower TS in dogs that died is likely a result of an acute phase reaction with downregulation of albumin synthesis in coordination with upregulation of inflammatory cytokines, increased vascular permeability, and loss of protein into the pleural effusion." (PMID 40417373, 2025). "SHAP analysis identified the retinol-binding protein 4 level, M. pneumoniae cycle-threshold value, D-dimer level, fever duration before admission, C-reactive protein-to-albumin ratio, and presence of pleural effusion as key predictors." (PMID 42112459, 2026). "Data required for utilization of the MTXPK tool were collected (age, sex, race, height, weight, MTX dose, creatinine, serum MTX, albumin, and the presence of pleural effusion)." (PMID 41710825, 2026). "Nevertheless, neutrophil leukocytosis, elevated inflammatory markers, and low serum albumin levels represent useful markers that should raise clinicians’ suspicion for purulent pleural effusion in children with complicated CAP." (PMID 40868554, 2025). "Low serum albumin levels facilitate fluid shift into the interstitial space, leading to extravascular fluid accumulation (such as ascites, pleural effusion, and intracranial effusion)." (PMID 40832604, 2025). "Poor nutritional status in elderly patients with reduced serum albumin, further leading to transudative pleural effusion." (PMID 40011204, 2025). "In univariate logistic analysis, atelectasis, pleural effusion, high neutrophil level, high CRP level, high D-dimer level, high LDH level, and low serum albumin level were remarkably associated with the risk of developing RMPP." (PMID 40654577, 2025). "Children developing pleural empyema have higher inflammatory markers and lower levels of serum albumin compared to patients with simple pleural effusion." (PMID 40868554, 2025). "In our data, albumin and total protein levels demonstrated the highest discriminative ability for pleural effusion, with a relatively high sensitivity but moderate specificity." (PMID 40428888, 2025). "A retrospective study identified several risk factors for the development of pleural effusion in elderly patients with CAP, including low serum albumin and low blood sodium levels." (PMID 40095877, 2025). "Protein levels were significantly lower in the pleural effusion group (median 6.04 vs. 6.42, p < 0.001), as were albumin levels (median 3.03 vs. 3.48, p < 0.001)." (PMID 40428888, 2025). "Protein exudation reduces albumin levels, resulting in hypo-osmotic plasma, which can lead to pleural effusion, further compromising blood oxygen saturation and destabilizing vital signs." (PMID 41268169, 2025). "The albumin/globulin (A/G) ratio was also lower in the pleural effusion group (median 1.05 vs. 1.16, p = 0.027), while the CRP/albumin (CRP/A) ratio was significantly higher in patients with pleural effusion (2.84 vs. 0.839, p < 0.001)." (PMID 40428888, 2025). "Decreased serum albumin level 6 h after surgery significantly impacted left-side pleural effusion development (median = 35, [IQR] 33–37) vs. (median = 36, IQR 34–38), U = 4264.5, z = −2.243, p = 0.025, V = 0.145)." (PMID 39336439, 2024).
Pleural effusion (continued). "The most common treatments for patients with pleural effusion by doctors in our dialysis center were improving dialysis adequacy, infusion of albumin, increasing diuresis, and transient automated peritoneal dialysis (APD) or thoracentesis." (PMID 38241413, 2024). "Our main objective was to evaluate the effectiveness of albumin addition in the cardiopulmonary bypass priming solution compared to standard priming, focusing on its role in reducing pleural effusion development." (PMID 39768615, 2024). "Increased ADM values have also been correlated with low albumin levels and increased pleural effusion." (PMID 39458091, 2024). "Two patients with pleural effusion improved after puncture drainage and albumin supplementation, and the rest improved after conservative treatment." (PMID 38539123, 2024). "The patient also exhibited pleural effusion, primarily due to undernutrition, with a serum albumin level of less than 2 g/dL, lymphocyte count of 835 cells/μL, and total cholesterol level of 160 mg/dL." (PMID 38233703, 2024). "An albumin level <35 g/L after the surgery showed a significant increase in pleural effusion development, and 100 mL of 20% albumin was sufficient to maintain serum albumin levels > 35 g/L." (PMID 39768615, 2024). "Biochemical examination of pleural effusion: Glucose: 7.38 mmol/L; Protein: 43.4 g/L; Albumin: 28.0 g/L; Chlorine: 108.9 mmol/L; Pleural LDH: 636 U/L; ADA:2U/L." (PMID 36747130, 2023). "Regarding variables that had a linear correlation with the AI-CXR score, CRP, albumin, and lymphocyte percentage showed a close correlation across all time categories with both consolidation and pleural effusion scores." (PMID 37762792, 2023). "PRP application in aortic arch replacement surgery reduced the transfusion of cryoprecipitate, increased the postoperative serum albumin and total protein levels, and reduced the incidence of pleural effusion." (PMID 37590313, 2023). "In our case report, it’s important to note that the patient had low levels of albumin and pleural effusion from the start of their hospitalization." (PMID 37241051, 2023). "This is due to the fact that, when compared to pleural effusion, pericardial fluid is characterized by higher levels of protein, albumin, nucleated cells (especially mesothelial cells) and very high levels of LDH." (PMID 37241003, 2023). "IGRA, CRP, ESR, serum TP, ALB, ADA, LDH, Pleural effusion TP, ALB, ADA, and LDH are the primary examinations for hospitalized patients." (PMID 37940883, 2023). "This study compares the diagnostic value of Light’s criteria, the serum-effusion albumin gradient (SEAG) method, and pleural effusion glucose levels for accurately categorizing pleural effusion as transudate or exudate." (PMID 37577277, 2023). "Because of high platelet concentrations and various growth factors, PRP application in aortic arch replacement surgery reduced the transfusion of cryoprecipitate, increased serum albumin and total protein levels, and reduced the incidence of pleural effusion." (PMID 37590313, 2023). "The pleural effusion biomarkers include neutrophils, PH, total protein, albumin, glucose, LDH, VEGF and survivin." (PMID 35209915, 2022). "A nomogram consisting of albumin, serum creatinine, glucose, and pleural effusion is also useful for the prediction of SAP." (PMID 35755843, 2022). "A nomogram consisting of albumin, serum creatinine, glucose, and pleural effusion was useful for prediction of SAP." (PMID 35755843, 2022). "The tool for predicting ICU admission composed of the following factors: respiratory rate, dyspnea, lung moist rales, LDH, BUN, C-reactive protein/albumin ratio, and pleural effusion." (PMID 36424963, 2022). "A nomogram comprising albumin, serum creatinine, glucose, and pleural effusion is a useful predictor of SAP." (PMID 35755843, 2022).
Pleural effusion (continued). "We examined the effect of pleural effusion drainage on nutritional factors such as serum albumin and on renal function, finding a small downward trend seven days after pigtail drainage." (PMID 36498795, 2022). "The presence of enlarged lymph nodes was associated with increased neutrophil counts, whereas pleural effusion with increased LDH and creatinine concentrations, reduced albumin and reduced oxygen saturation levels." (PMID 33557778, 2021). "They found that TP and albumin in pleural effusions are stable for a week regardless if stored at 21°C or - 20°C." (PMID 32292279, 2020). "The patient received antibiotics, she was transfused by red blood cells and platelets concentrates, she also received albumin with the pleural effusion drainage." (PMID 32774637, 2020). "Further prospective trials are required to determine the effect of exogenous albumin administration on reducing the incidence of postoperative pleural effusion following living donor hepatectomy." (PMID 30808903, 2019). "The minimum level of serum albumin (Albmin) in the postoperative data tended to correlate negatively with the volume of pleural effusion." (PMID 31194145, 2019). "The final logistic regression function was: log (odds of SAP) = 0.55 + 1.02 (SIRS)–0.63 (albumin) + 1.76 (BUN) + 1.66 (pleural effusion)." (PMID 31068202, 2019). "Despite the emphasis on the safety of donors, little is known about the impact of postoperative albumin level on pleural effusion in liver donors." (PMID 30808903, 2019). "This replacement resulted in higher postoperative albumin levels and lower incidence of pleural effusion in LDLT donors from 2013 to 2014 compared to those from 2010 to 2012." (PMID 30808903, 2019). "We further assessed the effect of intraoperative albumin solution infusion instead of synthetic colloid on postoperative albumin levels and the incidence of pleural effusion in donors who underwent hepatectomy from 2010 to 2014 (n = 1021)." (PMID 30808903, 2019). "When we further analysed data from 2010 to 2014, intraoperative albumin infusion was associated with higher POD2ALB (P < 0.001) and lower incidence of pleural effusion (P = 0.024), compared with synthetic colloid infusion after PS matching (193 pairs)." (PMID 30808903, 2019). "The analysis of donors from 2004 to 2012 showed that postoperative pleural effusion occurred in 47.4% (970/2046), and serum albumin levels decreased until postoperative day 2 (POD2) and increased thereafter." (PMID 30808903, 2019). "A prognostic score (We denoted it as the SABP score), ranging from 0 to 10, consisting of systemic inflammatory response syndrome, serum albumin, blood urea nitrogen and pleural effusion, was developed by logistic regression and bootstrapping analysis." (PMID 31068202, 2019). "We also assessed the effect of intraoperative use of albumin solution instead of synthetic colloid on postoperative albumin levels and the incidence of pleural effusion." (PMID 30808903, 2019). "Improved preservation of liver functions in LH maintains enough albumin synthesis and decreases the pleural effusion." (PMID 29686975, 2018). "Other markers of plasma leakage such as lower albumin levels, pleural effusion and fluid accumulation with respiratory distress were higher amongst the obese patients, although statistical significance was attained only for lower albumin levels." (PMID 30016369, 2018). "A previous study reported that an elevated AST level, a lower albumin concentration, the hematocrit peak, the lowest platelet count, and increased detectable of pleural effusion/ascites by USG were found in the critical phase or 1–2 days after defervescence." (PMID 29471786, 2018). "As for liver resection group, we found pleural effusion (4 cases) and perihepatic effusion (2 cases), and then we transfused the albumin and regulated the balance of electrolyte." (PMID 28881688, 2017).